IGF2BP3 (insulin like growth factor 2 mRNA binding protein 3)
Diseases named in the same sentence as IGF2BP3 in open-access papers (continued):
Sharing a sentence is not in itself a finding about the gene and the disease.
cancer (continued). "However, of the three family members, IGF2BP3 has been associated the most with distinct cancer types." (PMID 23069990, 2013). "The association between IGF2BP3 and m6A regulation is manifested at three levels: molecular mechanism (direct recognition and dependence on m6A modification), functional role (modulating RNA metabolism and fate via m6A), and disease relevance (serving as a central m6A effector in cancer)." (PMID 41589308, 2025). "Thus, IGF2BP3 might represent significant value as diagnostic and prognostic biomarkers in the individualized precision cancer therapy." (PMID 36761737, 2023). "In addition, the circulating IGF2BP3 protein levels, recently detected in serum from prostate cancer and renal cell carcinoma patients, were found to be associated with a significantly higher risk of cancer-specific death or relapse." (PMID 32010687, 2019). "IGF2BP3 has been largely investigated in various cancers, such as promoting cancer progression and indicating a worse prognosis for patients." (PMID 41350940, 2026). "Recently, the pathological implications of IGF2BP3 in different types of cancers have been well-documented." (PMID 41350940, 2026). "While several recent studies have demonstrated that cancer-specific gene regulatory effects of IGF2BP3 are m6A dependent, our work brings up the intriguing possibility that the effect on metabolism-related genes is m6A independent." (PMID 41015030, 2025). "We further confirmed this classification by calculating the average expression of IGF2BP1, IGF2BP2, and IGF2BP3 across cancer types and clusters, which consistently showed the highest levels in IGF2BP-H, intermediate in IGF2BP-M, and lowest in IGF2BP-L." (PMID 41049442, 2025). "The oncogenic properties of the RNA-binding protein IGF2BP3 have been studied across many different cancer types, including AML71,72." (PMID 40389480, 2025). "While our study provides evidence for the role of IGF2BP3 in the metabolic control of the cancer cell epitranscriptome, many questions remain unanswered." (PMID 41015030, 2025). "Subsequently, our knockdown of IGF2BP3 significantly inhibited cancer cell proliferation and induced apoptosis." (PMID 40801655, 2025). "Specifically, increasing evidence suggests that circRNAs have the capacity to control numerous cancer-related biological activities via interactions with IGF2BP3." (PMID 40418151, 2025). "The IGF2BP3 gene is ubiquitously expressed in eukaryotic tissues, and it is frequently upregulated in cancer cells in humans." (PMID 40418151, 2025). "IGF2BP3, an m6A reader, is part of the insulin-like growth factor II mRNA-binding proteins (IGF2BPs) family and is highly expressed in various cancers, including NSCLC." (PMID 40770637, 2025). "Pan-cancer analysis revealed elevated IGF2BP3 expression across various cancer types, particularly in liver tumors, compared with that in peritumor tissues." (PMID 40860202, 2025). "Insulin-like growth factor II mRNA binding protein 3 (IGF2BP3) is an RNA-binding protein and a key m6A reader that regulates various cancers through m6A-dependent mechanisms." (PMID 40083693, 2025). "IGF2BP3 is a key biomarker for systemic malignancies and has a strong correlation with many different forms of cancer." (PMID 40919129, 2025). "Insulin-like growth factor 2 mRNA binding protein 3 acts as a cancer-promoting agent in GC, enhancing the proliferation and migratory activities of GC cells." (PMID 40418151, 2025). "The biological functions of IGF2BP3 in cancer are typically related to mRNA splicing, stability, and translational regulation." (PMID 40418151, 2025). "It has been demonstrated that IGF2BP3 shows an abnormal expression pattern in a variety of malignant tumors." (PMID 40801655, 2025). "Upon binding to m6A modifications, IGF2BP3 promotes cancer by recruiting specific adaptor proteins to protect target mRNAs from degradation by exonuclease complexes." (PMID 41589308, 2025).
cancer (continued). "IGF2BP3, a carcinoembryonic protein highly expressed during embryonic development, is upregulated in various cancers, including GBM11." (PMID 38167409, 2024). "The expression level of IGF2BP3 exhibits a significant increase in TCGA-LGG or TCGA-GBM cancer tissues compared to normal tissues." (PMID 38429265, 2024). "Survival analysis based on the TARGET and TCGA databases revealed that only IGF2BP3 was positively associated with poor prognosis in AML and pan-cancer patients." (PMID 38822351, 2024). "IGF2BP3 is an oncofetal protein related to pro-tumorigenesis in various cancer types by regulating target mRNA at the post-transcriptional level." (PMID 38177154, 2024). "Analysis of DEGs between normal cervical tissue and cancer tissue revealed IGF2BP3 as a common target gene for ATL III in both HeLa and SiHa cells." (PMID 38358034, 2024). "The results showed that IGF2BP3 maintains a close relationship with these immune cells in pan-cancer tissues, except for MESO." (PMID 38577615, 2024). "Survival analysis using The Cancer Genome Atlas further indicates that IGF2BP3 can independently predict prognosis for patients with UM." (PMID 38686044, 2024). "The study provides a perspective on how IGF2BP3 is engaged in regulating of cancer growth and survival." (PMID 38429265, 2024). "We obtained the expression data of IGF2BP3 before and after cytokine treatment in various of cancer cell lines through TISMO database." (PMID 38577615, 2024). "Previous studies have demonstrated the critical role of M6A regulators FTO, IGF2BP2 and IGF2BP3 in ovarian and other cancers." (PMID 38714753, 2024). "IGF2BP3 expression was upregulated in various types of cancer tissues including LUSC tissues in comparison with normal tissues, as analyzed through the TIMER database." (PMID 39506204, 2024). "The pan-cancer analysis revealed upregulation of IGF2BP3 expression in a diverse range of human cancers." (PMID 38429265, 2024). "Recent studies have also highlighted the involvement of lncRNAs in interacting with IGF2BP3, influencing the progression of cancer." (PMID 38760723, 2024). "We proceeded to analyze the association between their expression and overall survival across a range of human cancers and found that IGF2BP3 expression was significantly correlated with shorter survival time in many cancer types." (PMID 38429265, 2024). "The enhancement of cancer proliferation, metastasis, and lipid metabolism was achieved through the regulation of stearoyl-CoA desaturase mRNA m6A modifications by the IGF2BP3-METTL14 complex." (PMID 38540406, 2024). "The expression of IGF2BP3 is found to be significantly different across stages I–IV in a few cancer types, and across T1–T4 groups." (PMID 39457524, 2024). "The expression pattern of a representative gene, IGF2BP3, varies significantly across N0–N3 groups and between M0 and M1 groups in some cancer types, respectively." (PMID 39457524, 2024). "Kaplan-Meier analysis showed that high IGF2BP3 expression was associated with poor survival prognosis in patients with AEG and TCGA pan-cancer." (PMID 39247830, 2024). "IGF2BPs, particularly IGF2BP1 and IGF2BP3, are oncofetal proteins and exhibit significantly up-regulated expression and prognostic correlation in various human cancers." (PMID 37280679, 2023). "Consistently, in vivo assays revealed that IGF2BP3 knockdown attenuated the RCC cancer stemness and inhibited orthotopic xenografts growth while overexpression of circRARS impaired the inhibition." (PMID 38073586, 2023). "Further, we found that the expression of IGF2BP3 was positively related to the MSI in 6 cancers, including LUSC, BLCA, TGCT, ESCA, SARC, and COAD, but had a negative correlation with MSI in SKCM, THCA, HNSC, and DLBC." (PMID 36761737, 2023).
cancer (continued). "H&E staining results also showed that the mutant IGF2BP3 group displayed fewer cancer cells, smaller cell sizes and accumulated chromatin condensation compared with the wild‐type IGF2BP3 group." (PMID 37877353, 2023). "Previous studies have shown that IGF2BP3 levels are abnormally high in a variety of cancers and acts as an oncogene in various tumors, including GC." (PMID 37340423, 2023). "Further, the RNA-binding protein IGF2BP3 has previously been implicated in the progression of AML and other cancers." (PMID 37709843, 2023). "We aimed to demonstrate the relationship between IGF2BP3 expression and pan-cancer using The Cancer Genome Atlas (TCGA) database." (PMID 36732736, 2023). "In the present study, firstly, we used multiple databases to evaluate the expression level of IGF2BP3 across pan-cancer." (PMID 36761737, 2023). "Functionally, IGF2BP3 can bind to and maintain the stability of downstream mRNAs to promote cancer progression, such as CDK4 and CDK6." (PMID 37407973, 2023). "Nevertheless, there is still a lack of comprehensive and systematic studies assessing the impact of IGF2BP3 on multiple cancer types." (PMID 36761737, 2023). "In clear-cell RCC, IGF2BP3 contributes to cancer progression and metastasis through activation of the NfKB pathway." (PMID 37760460, 2023). "As a member of the IGF2BP-family, IGF2BP3 regulates a number of genes involved in cancer cell proliferation, invasion, metastasis, and tumorigenesis." (PMID 36732736, 2023). "IGF2BP3 is highly overexpressed in cancer cells, and its expression correlates with a poor prognosis in various tumors." (PMID 37582618, 2023). "High levels of IGF2BP3 were measured in the majority of cancer cell lines except CaSki and SiHa and the normal cell line HcerEpic." (PMID 37877353, 2023). "At the transcriptional level, the transcription factors Nanog and NF‐κB bind to the IGF2BP3 promoter region and up‐regulate its expression for stemness maintenance and migration properties of cancer cells." (PMID 37877353, 2023). "IGF2BP3 is a member of the IGF2BPs family, which are consider having a marked impact on cancer occurrence and development." (PMID 37137710, 2023). "We believe that dysregulation of IGF2BP3 results in abnormal accumulation of oncogenic proteins, therefore supporting the malignant state of cancer." (PMID 37877353, 2023). "Results from combined databases revealed that IGF2BP3 was over-expressed significantly in 31 out of 34 cancer types (exceptions were READ, TGCT, and PCPG)." (PMID 36761737, 2023). "In this present study, we attempted to investigate the biological function and molecular mechanism of IGF2BP3 and assess its feasibility as potential cancer biomarker." (PMID 36732736, 2023). "Comparing STS to a TCGA cohort of pan-cancer, unsurprisingly, we found a range of IGF2BP3 expression across different cancer types." (PMID 37760460, 2023). "Knockdown of IGF2BP3 inhibits cancer cell growth, motility, and the features of aggressive cancer in a variety of cancer subtypes." (PMID 37760460, 2023). "This cancer’s single-cell state atlas revealed a positive correlation of IGF2BP3 with angiogenesis, differentiation, inflammation, metastasis, and quiescence." (PMID 36761737, 2023). "Next, we verified the expression of IGF2BP3 between cancer tissues and adjacent normal tissues at protein level using the HPA database." (PMID 36761737, 2023). "Herein, we initially analyzed the IGF2BP3 alteration status across multiple cancer types using cBioPortal database." (PMID 36761737, 2023). "The post‐translational regulation of IGF2BP3 also provides new insights into epigenetic changes in cancer." (PMID 37877353, 2023). "Some plant extracts, such as isoliquiritigenin, berberine, and an isocorydine derivative (d-ICD) have been shown to decrease IGF2BP3 expression, subsequently inhibiting the malignant behavior of cancers." (PMID 37280679, 2023).
cancer (continued). "We further injected limiting numbers (1 × 106, 1 × 105, 1 × 104) of the indicated cells into nude mice to evaluate the function of IGF2BP3 in regulating the cancer stem cell (CSC) properties of NPC in vivo." (PMID 37853162, 2023). "We anticipate that our modified PAR-CLIP protocol can be utilized for characterizing IGF2BP3 targets as well as studying other RBPs in various tissues and cancer cells." (PMID 37582618, 2023). "Previous studies have suggested that the major mechanism for IGF2BP3 as an oncogene is to stabilize its target genes, consequently promoting the proliferation and metastasis of cancer cells." (PMID 37658049, 2023). "Especially, there is growing evidence that circRNAs can regulate the biological processes of numerous cancers through IGF2BP3 interactions." (PMID 37340423, 2023). "This study highlights the manifold roles of IGF2BP3 in pan-cancer, which is promising as a prospective biomarker and potential target for cancer therapy." (PMID 36761737, 2023). "This study elucidates a critical role of m6A modification in shaping cancer cell plasticity via the IGF2BP3/MCM5/Notch axis." (PMID 37171793, 2023). "In accordance with the results, there was a strong correlation between IGF2BP3 and most immune-related genes in specific cancer types such as GBMLGG, LGG, LUAD, PAAD, BRCA, and PRAD." (PMID 36761737, 2023). "In the present study, IGF2BP3 overexpression predicted worse survival in STS, consistent with its known association with poor prognosis in a growing list of cancer types." (PMID 37760460, 2023). "IGF2BP3 has been demonstrated to promote cancer progression by being stabilized by ncRNAs and stabilizing mRNA of downstream genes." (PMID 37965577, 2023). "We found that IGF2BP3 was ubiquitously highly expressed in pan-cancer and significantly correlated with diagnosis, prognosis, TMB, MSI, and drug sensitivity in various types of cancer." (PMID 36761737, 2023). "Then, we outline the role and specific mechanisms of IGF2BP3 in tumors in either m6A-dependent or m6A-independent manners to provide new insights for the treatment of malignant tumors." (PMID 37298373, 2023). "Specifically, chemokines such as CXCL9, CXCL10, and CXCL11 and chemokine receptors such as CXCR5, CCR4, CCR8, and CCR1 were positively correlated with IGF2BP3 expression in various cancer types." (PMID 36761737, 2023). "Many studies had shown that IGF2BP3 was overexpressed in various cancers, including gastric cancer, lymphoid malignancies, nasopharyngeal cancer, and renal cell carcinoma, and that its overexpression correlates with a poor prognosis for overall survival." (PMID 36732736, 2023). "Although we have explored the pan-cancer role of IGF2BP3 from the perspective of bioinformatics in depth, we must acknowledge some limitations in the present study." (PMID 36761737, 2023). "Further comparison between the tumors and adjacent normal tissues displayed that the expression level of IGF2BP3 was upregulated in most types of human cancers." (PMID 36761737, 2023). "The expression of ENO2 and IGF2BP3 in cancer tissues was higher than that in adjacent normal tissues." (PMID 37644235, 2023). "We further investigated the relationship between IGF2BP3 expression and immune cell infiltration in pan-cancer levels using immune cell infiltration data extracted from various databases." (PMID 36761737, 2023). "Usually, IGF2BP3 exerts its biological functions in cancers via regulation of mRNA cleavage and stability and through translational regulation." (PMID 37340423, 2023). "To evaluate the functional state of IGF2BP3 in various cancer types at the single-cell level, we analyzed the correlation of IGF2BP3 with multiple functional states of cancer cells via the CancerSEA." (PMID 36761737, 2023). "Recent studies have shown that IGF2BP3 can interact with non-coding RNA to regulate cancer progression." (PMID 37340423, 2023).
cancer (continued). "m6A modification has gradually become the focus of cancer research, but the role of IGF2BP3 in this process is still poorly understood." (PMID 37298373, 2023). "IGF2BP3 staining was homogenous and localized to the cytoplasm in positive samples, similar to previously validated cancers." (PMID 37760460, 2023). "Correlation of IGF2BP3 differential expression with molecular subtypes in pan-cancer was investigated by the TISIDB database." (PMID 36761737, 2023). "Insulin-like growth factor-2 mRNA-binding proteins (IGF2BPs), IGF2BP1 and IGF2BP3, are evolutionarily conserved families of RNA-binding proteins that regulate important parts of cancer cells and promote the development of cancers." (PMID 36727069, 2022). "IGF2BP3 is expressed during embryogenesis, lowly expressed in healthy adult tissues, and strongly reexpressed in cancer cells." (PMID 34321607, 2022). "IGF2BP3 regulates mRNA expression in normal and cancer cells so we attempted to identify the target mRNAs regulated by circARID1A-IGF2BP3." (PMID 35986300, 2022). "As an RNA binding protein, IGF2BP3 modulates the stability of multiple mRNAs to facilitate cancer development." (PMID 35676262, 2022). "A major function of IGF2BP3 is interaction with the mRNA machinery, and plays as a stabilizer of oncogene in cancer." (PMID 35541906, 2022). "All human IGF2BPs have been identified as oncofetal proteins, and among them, IGF2BP1 and IGF2BP3 are bona fide oncofetal proteins that are synthesized in many cancers." (PMID 35541906, 2022). "Numerous studies have shown that IGF2BP3 is ubiquitously expressed in eukaryotic tissues and is often up-regulated in human cancers." (PMID 34986849, 2022). "Based on The Cancer Genome Atlas (TCGA) databases, Zhou and colleagues discovered that overexpression of insulin-like growth factor 2 mRNA-binding protein 3 (IGF2BP3) was related to cancer progression and poor survival of patients." (PMID 35620395, 2022). "Over the past few years, studies have increasingly documented the contribution of IGF2BP3 to fundamental processes in cancer biology, such as cell growth, migration, and the response to drugs." (PMID 36338681, 2022). "Studies have found that IGF2BP3 can stabilize CDKN2B-AS1 through epigenetic activation of NUF2 transcription to drive the progression of KIRC malignant tumors." (PMID 36098680, 2022). "Immunofluorescence staining and qRT-PCR analyses also showed that the expression of IGF2BP2 and IGF2BP3 were higher in cancer tissues than that in adjacent normal tissues." (PMID 36686749, 2022). "Immunohistochemistry and qPCR were used to analyze the difference between IGF2BP3 protein and mRNA expression in cancer tumors and adjacent tissues." (PMID 35677634, 2022). "For example, lncRNA PCAT6 bound to RBM15 and IGF2BP3 in several cancer cell lines, which were determined by CLIP and eCLIP technology." (PMID 36032659, 2022). "Mechanistically, akin to IGF2BP1, IGF2BP3 protects let-7 target transcripts, including HMGA2 and LIN28B, by disrupting RISC association and upregulating expression in development and cancer." (PMID 36307883, 2022). "Knocking down HNRNPC and IGF2BP3 in cancer cells led to decreased levels of SAE1, probably through the regulation of mRNA stability." (PMID 35859792, 2022). "Together, these data demonstrate that IGF2BP3 plays a major role in amplifying the expression of many cancer-related genes in Lin− and CD11b+ cells." (PMID 34321607, 2022). "What’s more, IGF2BP3/ELAVL1 complex leads to prolonged half-lives of cancer-related mRNA molecules and increased expression of the target genes." (PMID 35276059, 2022). "M6A-associated proteins exhibit widespread epigenetic alterations across 33 cancer types, in which the m6A reader IGF2BP3 (also known as IMP3, KOC) is significantly correlated with adverse outcomes." (PMID 35136045, 2022). "For instance, the IGF2BP3 that newly identified as N6‐methyladenosine (m6A) reader, is reported to mainly play oncogenic roles in multiple types of cancer." (PMID 35593226, 2022).